EPPK1 (epiplakin 1)
Description:
Cytoskeletal linker protein that connects to intermediate filaments and controls their reorganization in response to stress. In response to mechanical stress like wound healing, is associated with the machinery for cellular motility by slowing down keratinocyte migration and proliferation and accelerating keratin bundling in proliferating keratinocytes thus contributing to tissue architecture. However in wound healing in corneal epithelium also positively regulates cell differentiation and proliferation and negatively regulates migration thereby controlling corneal epithelium morphogenesis and integrity. In response to cellular stress, plays a role in keratin filament reorganization, probably by protecting keratin filaments against disruption. During liver and pancreas injuries, plays a protective role by chaperoning disease-induced intermediate filament reorganization (By similarity).
Synonyms: EPIPL; EPIPL1
Tractability: Antibody: UniProt places it where antibodies can reach, with medium confidence; its Gene Ontology location is reachable by antibodies, with medium confidence. PROTAC: ubiquitination databases record sites on it; its protein half-life has been measured.
Gene: Protein-coding gene on chromosome 8 (143,857,324 to 143,878,467, reverse strand). Ensembl gene ENSG00000261150.
Subcellular location: Cytoplasm, cytoskeleton; Cell junction, hemidesmosome; Cell junction, tight junction; Cell projection; Apicolateral cell membrane; Basolateral cell membrane; Cell junction
Subcellular location (Human Protein Atlas): Intermediate filaments
Gene Ontology:
Molecular function: intermediate filament binding; RNA binding; keratin filament binding; structural molecule activity
Biological process: intermediate filament organization; negative regulation of cell migration; negative regulation of epithelial cell proliferation; negative regulation of wound healing; wound healing; intermediate filament bundle assembly; negative regulation of keratinocyte migration; negative regulation of keratinocyte proliferation; regulation of epithelium regeneration; intermediate filament cytoskeleton organization
Cellular component: bicellular tight junction; cell periphery; cytoskeleton; hemidesmosome; intermediate filament cytoskeleton; keratin filament; perinucleolar compartment; cell junction; cytoplasm; intermediate filament; membrane; anchoring junction; apicolateral plasma membrane; basolateral plasma membrane; cell-cell junction
Genetic constraint (gnomAD): Loss-of-function variants: 1 observed, 0.47 expected, observed/expected ratio (o/e) 2.11. That is too few expected variants to judge how well the gene tolerates losing a copy. Missense variants: 3,637 observed, 2,989.4 expected, observed/expected ratio (o/e) 1.22, 90% interval 1.18 to 1.25. Synonymous variants: 1,759 observed, 1,365.8 expected, observed/expected ratio (o/e) 1.29, 90% interval 1.24 to 1.34.
Homologues: Orthologues: rat Eppk1 (65% identical), pig EPPK1 (57% identical), mouse Eppk1 (51% identical), tropical clawed frog eppk1 (39% identical). Paralogues in human: PLEC (19% identical), DSP (9% identical), MACF1 (7% identical), DST (6% identical), SYNE1 (6% identical), SYNE2 (5% identical), SPTBN5 (5% identical), SPTBN4 (4% identical), UTRN (4% identical), SPTBN2 (4% identical), FLNC (4% identical), DMD (4% identical), and 24 more.
Diseases named in the same sentence as EPPK1 in open-access papers:
EPPK1 is named in the same sentence as 31 diseases in open-access papers, as found by Europe PMC text mining. Sharing a sentence is not in itself a finding about the gene and the disease. The quoted sentences say what the papers report.
cervical cancer (6 papers, 2021 to 2024). A primary or metastatic malignant neoplasm involving the cervix. "Previous reports have described the association of EPPK1 with poor prognosis in hepatocellular cancer and esophageal squamous cell cancer, as well as its potential as a biomarker for pancreatic and cervical cancer." (PMID 38594604, 2024). "Our data showed that EPPK1 expression is associated with short survival, which is partially coherent with previous studies that have shown that EPPK1 expression activates cell proliferation in cervical cancer and esophageal squamous cell carcinoma." (PMID 36836422, 2023). "Activation of fluorescent-labelled EPPK1 in HeLa cells, originally of cervical cancer origin, demonstrated dynamic movement of EPPK1 protein, from one side of the cell membrane to another during migration." (PMID 34001250, 2021). "This work excites attention on the role of Eppk1 in CC and gives the direction for future research, contributing to a novel molecular target for the clinical diagnosis and treatment of cervical cancer." (PMID 33827480, 2021). "Different expression levels of Eppk1 have been found in various cancers, such as hepatocellular carcinoma, cervical cancer, and bladder urothelial carcinoma, but the role of Eppk1 in BLCA remains unknown." (PMID 37328487, 2023). "To examined whether levels of Eppk1 would alter in cervical cancer, we performed RNA expression profiling using RNA-sequence analyses of human CC tissues (n = 3) and normal cervical tissues (n = 3)." (PMID 33827480, 2021). "Eppk1 may be an effective therapeutic target for affecting p38 signaling pathway and cell proliferation in cervical cancer." (PMID 33827480, 2021). "Therefore, up-regulation of Eppk1 expression might shed light on initiation and development of cervical cancer." (PMID 33827480, 2021). "EPPK1 is part of the epidermal growth factor (EGF) signaling pathway and promotes cell growth in cervical cancer via the p38 signaling pathway." (PMID 35664780, 2022). "However, the role of Eppk1 in cervical cancer (CC) remains unknown." (PMID 33827480, 2021). "Besides, we also found the correlation between Eppk1 and KLF5 in cervical cancer using the TCGA database (R = 0.18, P < 0.01)." (PMID 33827480, 2021). "Because Eppk1 is a part of EGFR, and Eppk1 expression has a positive correlation with EGFR in CC from TCGA data (P < 0.05, R = 0.13), we further clarify the EGFR-related signaling pathways by which Eppk1 expression affects the proliferation of cervical cancer cells." (PMID 33827480, 2021).
hepatocellular carcinoma (3 papers, 2021 to 2024). A malignant tumor that arises from hepatocytes. "The varying expression of Eppk1 has found in various cancers such as hepatocellular carcinoma, bladder urothelial carcinoma, CC, and Eppk1 has also further studied in pancreatic cancer, but the role of Eppk1 in CC remains unknown." (PMID 33827480, 2021).
pancreatic cancer (2 papers, 2017 to 2021). "Eppk1 as a member of plakin family, expresses in various progenitors and developing and regenerating cells, especially in pancreatic cancer, suggesting that it could be a good marker for development of cancer cells." (PMID 33827480, 2021).
atopic dermatitis (1 paper, 2025). "To evaluate whether the observed downregulation of EPPK1 is specific to psoriasis or also occurs in other chronic inflammatory skin diseases, we performed a comparative analysis using atopic dermatitis (AD) another chronic inflammatory skin disorder to contextualize the psoriasis findings." (PMID 40746860, 2025).
breast carcinoma (1 paper, 2022). "The IHC score results demonstrated that ADAMTS12, AEBP1, CXCL11, and EPPK1 protein levels were higher in breast cancer samples than in normal controls." (PMID 35505821, 2022).
cervical intraepithelial neoplasia (1 paper, 2021). "Additionally, we performed immunofluorescence staining to examine co-expression of Eppk1 and KLF5 proteins in different pathologic cervical tissues (37 normal cervical tissues, cervical intraepithelial neoplasia (CIN) tissues (CIN I: 31 cases; CIN II-III: 47 cases) and 40 CC tissues)." (PMID 33827480, 2021).
cervical squamous cell carcinoma (1 paper, 2021). A squamous cell carcinoma arising from the cervical epithelium. "TCGA database further revealed the level of Eppk1 in cervical squamous cell carcinoma increases (P < 0.05)." (PMID 33827480, 2021).
chronic obstructive pulmonary disease (1 paper, 2024). A chronic and progressive lung disorder characterized by the loss of elasticity of the bronchial tree and the air sacs, destruction of the air sacs wall, thickening of the bronchial wall, and mucous accumulation in the bronchial tree. "Patient characteristics, such as age, gender, smoking history, histology, pathological stage, and chronic obstructive pulmonary disease status, were summarized by histology and EPPK1 protein expression." (PMID 38594604, 2024).
dyslipidaemia (1 paper, 2025). "Our study confirmed key proteins (PCSK9, ANGPTL3, LPA), identified potential novel targets (GSTA1, GSTA3, EPPK1, PECR, and PLA2G15), and strengthened evidence for CELSR2 and GAS6 in dyslipidaemia." (PMID 40689090, 2025).
esophageal cancer (1 paper, 2024). A primary or metastatic malignant neoplasm involving the esophagus. "Our results, comparing EPPK1 mRNA expression between cancer and normal tissues, support the evidence suggesting that EPPK1 is associated with poor prognosis in liver and esophageal cancers." (PMID 38594604, 2024).
Fanconi anaemia (1 paper, 2017). "Moreover, heterozygous mutations in Fanconi anaemia genes are associated with increased cancer risk, primarily BC, and indeed, two of the four AJP-specific deleterious variants in the EPPK1 gene were also detected in the high-risk BC cohort." (PMID 28502252, 2017).
glioma (1 paper, 2023). A benign or malignant brain and spinal cord tumor that arises from glial cells (astrocytes, oligodendrocytes, ependymal cells). "Inflammatory microglial cells, dendritic cells, myeloid cells, and glioma stem cells were highly expressed in GBM tissue, and ACP7, EPPK1, PCDHA8, RHOD, DRC1, ZIC3, and PRLR were significantly associated with survival." (PMID 36836422, 2023).
Hyperkeratosis (1 paper, 2025). Hyperkeratosis is a histopathological term defining a thickened stratum corneum and may be present in many different skin conditions, with many possible overlaps. "Interestingly, cetacean skin exhibits morphological parallels to psoriatic epidermis, including thickening, hyperkeratosis, and parakeratosis, raising intriguing questions about the evolutionary role of EPPK1 in barrier adaptation." (PMID 40746860, 2025).
inflammatory skin disorders (1 paper, 2025). "While most plakins are critical for maintaining epidermal integrity, the role of epiplakin (EPPK1) in inflammatory skin disorders has not been thoroughly investigated." (PMID 40746860, 2025).
intrahepatic cholangiocarcinoma (1 paper, 2016). A carcinoma that arises from the intrahepatic bile duct epithelium in any site of the intrahepatic biliary tree.
liver disease (1 paper, 2015). "After four weeks of DDC feeding, Eppk1−/− mice displayed significantly elevated ALT serum levels compared to WT mice, indicating a more severe course of liver disease." (PMID 25617501, 2015).
lung adenocarcinoma (1 paper, 2024). A carcinoma that arises from the lung and is characterized by the presence of malignant glandular epithelial cells. "We recently found that epiplakin 1 (EPPK1) alterations were present in 12% of lung adenocarcinoma (LUAD) cases and were associated with a poor prognosis in early-stage LUAD when combined with other molecular alterations." (PMID 38594604, 2024).
lung carcinoma (1 paper, 2024). "This suggests that EPPK1 plays a crucial role in the progression of lung cancer through the EMT signaling pathway, which is associated with tumorigenesis." (PMID 38594604, 2024). "Furthermore, RNA sequencing analysis, including GO enrichment analysis of selected molecular functions, indicated that EPPK1 mRNA is associated with lung cancer development." (PMID 38594604, 2024). "We demonstrated that smoking-induced inflammation, DNA damage, and genomic instability contribute to increased EPPK1 expression in normal bronchial epithelial cells, potentially promoting lung cancer development." (PMID 38594604, 2024). "EPPK1 protein was found to be expressed in the cytoplasm of resected lung cancer tissue and lung cancer cell lines." (PMID 38594604, 2024). "We conclude that smoking-induced DNA damage and genomic instability contribute to increased EPPK1 expression in normal bronchial epithelial cells, potentially promoting lung cancer development." (PMID 38594604, 2024). "Overall, our results strongly suggested that EPPK1 promotes EMT and lung cancer development." (PMID 38594604, 2024). "However, the specific role of EPPK1 in lung cancer has not been explored." (PMID 38594604, 2024).
melanoma (1 paper, 2022). A malignant, usually aggressive tumor composed of atypical, neoplastic melanocytes. "In univariate Cox proportional hazard regression analysis, 3 of 11 genes (FCGR2A, PDE3A, and EPPK1) were significantly related to the prognosis of patients with melanoma." (PMID 35664780, 2022). "To determine pairwise correlations involving MYBL2 expression and three genes (FCGR2A, PDE3A, and EPPK1), we reanalyzed the transcriptome data of melanoma cases from TCGA." (PMID 35664780, 2022). "When combined with the results of univariate Cox proportional hazard regression analysis, 3 of 11 genes (FCGR2A, PDE3A, and EPPK1) were related to the prognosis of patients with melanoma." (PMID 35664780, 2022). "Importantly, we identified three key genes (FCGR2A, PDE3A, and EPPK1) that were correlated with the survival of melanoma patients." (PMID 35664780, 2022). "In summary, these results revealed that three key genes (FCGR2A, PDE3A, and EPPK1) may be potential prognostic factors in patients with melanoma." (PMID 35664780, 2022). "Importantly, multivariate Cox regression and survival curve analysis revealed that PDE3A and EPPK1 were negatively correlated with melanoma patient survival; however, FCGR2A was positively correlated with patient survival." (PMID 35664780, 2022).
pancreatitis (1 paper, 2015). Inflammation of the pancreas. "Recently, we reported that Eppk1−/− mice suffered from aggravated experimentally-induced pancreatitis, and more of their acinar cells displayed keratin aggregates." (PMID 25617501, 2015).
prostate carcinoma (1 paper, 2013). A carcinoma that arises from epithelial cells of the prostate gland. "Also, the cytoskeleton associated genes EPPK1, a plakin family member, and the LIM and SH3 protein gene LASP1 fall in regions 8q24 and 17q12; the gains of both regions have been previously associated with prostate cancer progression." (PMID 23826159, 2013).
psoriasis (1 paper, 2025). An autoimmune condition characterized by red, well-delineated plaques with silvery scales that are usually on the extensor surfaces and scalp. "To investigate the role of EPPK1 in epidermal homeostasis and its potential involvement in psoriasis-associated transcriptional changes, we performed scRNA-seq of skin isolated from wildtype and Eppk1−/− mice." (PMID 40746860, 2025). "Investigation of the mechanism underlying the EPPK1 regulation in psoriasis revealed that interferon-γ (IFN-γ) was the main cytokine involved in its downregulation in human ex vivo skin." (PMID 40746860, 2025). "While the IMQ model supports the relevance of EPPK1 loss in inflammatory skin conditions, these limitations underscore the need for more refined models, such as Eppk1-deficient mice crossed with genetic models of psoriasis, to fully dissect the functional role of Eppk1 in psoriasis in vivo." (PMID 40746860, 2025). "We therefore used single-cell RNA sequencing (scRNAseq) analysis, immunofluorescence, and ex vivo cytokine treatment of human skin explants to investigate EPPK1 regulation in psoriasis." (PMID 40746860, 2025). "Further dissection of individual plakin family members expression revealed that EPPK1 stood out as the most significantly downregulated plakin in psoriasis." (PMID 40746860, 2025). "Despite its downregulation in psoriasis, the contribution of EPPK1 to epidermal homeostasis appears to be context- and species-dependent." (PMID 40746860, 2025). "We further aimed to investigate the factors responsible for the observed downregulation of EPPK1 in psoriasis." (PMID 40746860, 2025). "We identify IFN-γ as a key upstream regulator of EPPK1 in psoriatic lesions and propose that EPPK1 downregulation contributes to disrupted differentiation and weakened barrier function in psoriasis." (PMID 40746860, 2025). "Consequently, we further concentrated our study on EPPK1 in psoriasis, using immunostaining to validate the mRNA expression results from the scRNAseq analysis." (PMID 40746860, 2025). "To explore whether EPPK1 downregulation is conserved in mouse models of psoriasis, we performed scRNA-seq analysis of skin from wild-type and imiquimod (IMQ)-treated mice." (PMID 40746860, 2025). "Given that EPPK1 protein expression is most prominent in late-stage differentiated keratinocytes, its reduction in psoriasis may contribute primarily to disrupted differentiation rather than the hyperproliferation that characterizes the disease." (PMID 40746860, 2025). "In psoriasis, chronic inflammation, particularly mediated by IFN-γ, IL-17A, and IL-22, may override any anti-proliferative effect of EPPK1 loss." (PMID 40746860, 2025). "However, it remains unclear whether EPPK1 contributes directly to the barrier defect observed in psoriasis or if its downregulation is merely a bystander effect of impaired keratinocyte differentiation." (PMID 40746860, 2025). "Calculation of a plakin gene module score, comprising Dsp, Dst, Eppk1, Evpl, Macf1, Plec, and Ppl, revealed a broad reduction in the IMQ-treated condition, partially recapitulating the findings observed in human lesional psoriasis." (PMID 40746860, 2025). "Collectively, our findings demonstrate a specific IFN-γ-dependent downregulation of EPPK1 in psoriasis, suggesting that lack of EPPK1 might contribute to the epithelial defects observed in this inflammatory skin condition." (PMID 40746860, 2025). "Taken together with the reduced but largely preserved expression of key terminal differentiation markers FLG and CDSN, this pattern indicates that EPPK1 downregulation is unlikely to be solely a secondary consequence of impaired keratinocyte differentiation in lesional psoriasis." (PMID 40746860, 2025). "However, unlike EPPK1, EVPL and PPL were not downregulated in lesional psoriasis, indicating a unique role of EPPK1 in psoriatic pathogenesis." (PMID 40746860, 2025).